GHRH (growth hormone releasing hormone)
Diseases named in the same sentence as GHRH in open-access papers (continued):
Sharing a sentence is not in itself a finding about the gene and the disease.
metabolic disorders (3 papers, 2024 to 2025). "These beneficial effects highlight the potential of GHRH agonists and antagonists for clinical applications in treating human metabolic diseases or improving β-cell survival in transplantable cells." (PMID 40095316, 2025). "These beneficial effects strongly support the potential of GHRH agonists and antagonists for the clinical treatment of human metabolic diseases or for enhancing β-cell survival in cells used for transplantation." (PMID 39560873, 2024). "In patients with GHD, GH therapy can improve body composition, reduce fat mass, increase lean body mass, and improve lipid profiles, highlighting the therapeutic potential of targeting GHRH/GH pathways in metabolic disorders." (PMID 39560873, 2024). "Furthermore, we will discuss the potential beneficial effects of GHRH analogs for the treatment of metabolic diseases." (PMID 39560873, 2024). "Additionally, we explore the diverse functions of synthetic GHRH agonists and antagonists in both physiology and pathology, with a particular emphasis on their therapeutic potential in metabolic disorders." (PMID 39560873, 2024). "Growth Hormone-Releasing Hormone (GHRH) and its analogs have gained significant attention for their therapeutic potential across various domains, including oncology, regenerative medicine, and metabolic disorders." (PMID 39592529, 2024).
cardiac diseases (2 papers, 2024 to 2025). "Despite these hurdles, the compelling evidence supporting their role in cardiac repair makes GHRH analogs attractive candidates for clinical testing in the treatment of various cardiac diseases." (PMID 39883351, 2025). "Among a spectrum of GH secretagogues, many synthetic GHRH agonists have been developed, but few have been tested in experimental heart diseases." (PMID 39883351, 2025).
neurodegenerative disease (2 papers, 2024 to 2025). A disorder of the central nervous system characterized by gradual and progressive loss of neural tissue and neurologic function. "Additionally, GHRH antagonists are being investigated for their potential in treating neurodegenerative diseases and inflammatory conditions." (PMID 39592529, 2024).
hematological disorders (1 paper, 2024). "Expression of growth hormone-releasing hormone (GHRH) and its receptors (GHRH-R) has been previously demonstrated in various human tumors, but very limited findings are available about the presence and potential function of GHRH-Rs in oncological and hematological disorders of children." (PMID 39201517, 2024).
kidney disease (1 paper, 2009). "Results from these studies suggest that a clinical intervention such as EP of plasmid GHRH could preserve renal function and possibly improve the negative impact of kidney disease on health-related quality of life." (PMID 19149896, 2009).
GHRH also shares sentences with these, for which no sentence is quoted: pseudohypoparathyroidism type 1A (6 papers); somatotroph adenoma (6); glioma (5); Cushing syndrome (4); depression (4); hypogonadism (4); carcinoid tumor (3); empty sella (3); gastrinomas (3); insulinomas (3); arterial hypertension (2); cognitive disorder (2); endothelial dysfunction (2); heart failure (2); Hyperinsulinemia (2); hyperplasia (2); immune dysfunction (2); non-Hodgkin lymphoma (2); pseudohypoparathyroidism (2); pseudopseudohypoparathyroidism (2); somatostatinoma (2); teratoma (2); acute lymphoblastic leukemia (1); acute promyelocytic leukemia (1); adrenal adenoma (1); Adrenal insufficiency (1); AIDS (1); Albright hereditary osteodystrophy (1); Anorexia (1); Anterior hypopituitarism (1).
A further 70 diseases each share a sentence with GHRH in 1 paper.